TREM2 (triggering receptor expressed on myeloid cells 2)
Diseases named in the same sentence as TREM2 in open-access papers (continued):
Sharing a sentence is not in itself a finding about the gene and the disease.
tumor (continued). "CAFs are generally classified into myofibroblasts (myCAFs), which promote tumor progression and immune evasion via TREM2 TAMs, and inflammatory CAFs (iCAFs), which drive local inflammation response." (PMID 41228323, 2025). "Across all analyzed cell types, TREM2 expression was primarily confined to tumor tissues, whereas CD5L was more prevalent in normal tissues." (PMID 40552574, 2025). "These discoveries corroborate the view put forth by other researchers that TREM2 + macrophages contribute to the promotion of tumor progression." (PMID 41035074, 2025). "An increasing number of studies have indicated that TREM2 upregulation is a significant marker of immune suppression in the tumor microenvironment and promotes tumor progression in a vast majority of cancers." (PMID 40242752, 2025). "QRHXF enhanced antitumor immune responses in NSCLC via TREM2 and modulation of the PI3K/AKT/STAT6 signaling pathway, reducing chemotactic infiltration of M2 tumor-associated macrophages within the TME." (PMID 40670983, 2025). "Immunohistochemistry (IHC) demonstrated that, compared with adjacent normal tissue, TREM2 expression was enhanced in tumor tissues." (PMID 41253786, 2025). "The use of TREM2 inhibitors and similar tools selectively eliminates immunosuppressive macrophages, restores normal immune responses, and inhibits tumor growth." (PMID 40191203, 2025). "Immunohistochemistry and flow cytometry validated the high expression of TREM2 in tumor regions, particularly in the TAM-rich tumor microenvironment." (PMID 40725764, 2025). "Subsets like C1Q + TREM2 + macrophages are more abundant and closer to tumor cells, indicating a functional role related to their positioning." (PMID 41035074, 2025). "TREM2-positive macrophages are enriched in the BC microenvironment and are involved in immune suppression and tumor progression." (PMID 41394809, 2025). "In conclusion, these findings underscore that targeting multiple immune checkpoints and TREM2 macrophages in MMRd and MMRp tumors not only further curbs tumor growth but can also culminate in complete tumor eradication." (PMID 40027748, 2025). "In NSCLC, TREM2+ macrophages are highly enriched in tumour cores, where they physically and functionally restrict NK cell infiltration; antibody-mediated TREM2 blockade reactivates NK cells, highlighting a targetable axis of suppression." (PMID 40948757, 2025). "Targeting TREM2 presents a novel immunotherapeutic strategy aimed at reprogramming the myeloid compartment and enhancing anti-tumor immune responses." (PMID 40821795, 2025). "Given that TREM2 has distinct expression patterns and various functions in tumor progression, the mechanism by which the expression of TREM2 affects the immune microenvironment merits further investigation." (PMID 39838454, 2025). "This study aimed to evaluate the role of TREM2 in the tumor microenvironment in the context of HCC progression." (PMID 39838454, 2025). "OPA, a platinum (IV)-based compound derived from Oxaliplatin (OP) and Artesunate (ART), has been shown to diminish TREM2 expression in macrophages, facilitating their polarization from an immunosuppressive M2 phenotype to an anti-tumor M1 phenotype." (PMID 40552184, 2025). "TREM2 inhibition reduces tumor growth and extends survival by increasing infiltration of PD-1-positive cytotoxic T lymphocytes and reducing immunosuppressive macrophage numbers." (PMID 40427130, 2025). "In this context, tumor-derived apolipoprotein E (APOE) binds to TREM2 on TAMs, triggering downstream activation of the DAP12–SYK signaling cascade, which subsequently engages PI3K–AKT and MAPK pathways to initiate a neurogenic transcriptional program." (PMID 41009819, 2025). "CD14-positive cells localized to clusters 0, 3, 5, 6, and 14 and were classified as mutually exclusive TREM2 and FCN1 tumor-associated macrophages (TAMs), as previously reported." (PMID 41228323, 2025).
tumor (continued). "In triple-negative breast cancer (TNBC) and other aggressive breast cancers, TREM2+ macrophages accumulate within the tumor stroma and suppress effective immune priming." (PMID 40821795, 2025). "In contrast, ADC cell-derived exosomal circ_0001715 were reported to promote tumor cell proliferation and metastasis by increasing M2-type TAMs polarization via the miR-205-5p/TREM2 axis." (PMID 41023740, 2025). "qPCR and WB proved TREM2 increased significantly in tumor tissues at transcription and protein level." (PMID 41253786, 2025). "Conversely, TREM2 deficiency has been shown to mediate TME remodeling, significantly enhancing tumor resistance in mice compared to wild-type counterparts." (PMID 40670983, 2025). "In contrast, resistance is associated with upregulation of TIM3, LAG3, TIGIT, and PD-1 expression on T cells, and infiltration of the tumor with immunosuppressive TREM2+ macrophages and monocytes." (PMID 40027748, 2025). "AR-imprinted TREM2/SPP1 TAMs cluster near tumor nests, CAFs, and vasculature; specifically enriched in the bone metastatic niche." (PMID 41488638, 2025). "TREM2-expressing TAMs promote tumor progression through immunosuppression, driving CD8+ TILs dysfunction and NK cell paucity 47-50." (PMID 39744236, 2025). "Our findings suggest that targeting TREM2 can not only slow tumor progression and reshape the tumor immune microenvironment (TIME), but it can also improve the effectiveness of anti-PD-L1 therapy." (PMID 41253786, 2025). "Key microglia-associated genes, including TREM2 and CX3CR1, regulate immune suppression, tumor proliferation, and invasion, while IL-1β and TNF-α contribute to tumor-promoting inflammation." (PMID 40076502, 2025). "Within the tumor microenvironment, TREM2 plays an immunosuppressive role, negatively regulating antitumor immune responses." (PMID 41300781, 2025). "Currently, TREM2 (triggering receptor expressed on myeloid cells 2)+ TAMs drive tumor progression and immunotherapy resistance in HCC through SPP1-mediated effects on both cancer cells and CD8+ T cells." (PMID 41225975, 2025). "In contrast, other studies identified TREM2 as a tumor suppressor in HCC that acts via the PI3K/Akt/β-catenin pathway." (PMID 39838454, 2025). "Consistent with prior studies, we observed that TREM2, a well‐known marker of immunosuppressive macrophages in multiple cancers was highly expressed in the mac3 subtype within tumor tissues." (PMID 40552574, 2025). "The triggering receptor expressed on myeloid cells 2 (TREM2), predominantly situated within various myeloid cell types, plays a pivotal role in the modulation of neurodegeneration, inflammation, neoplasms, and other pathologies." (PMID 40552184, 2025). "Tumor lipids induced higher TREM2 expression in BMDMs derived from WT mice compared to control treatment, and further enhanced its expression in BMDMs from NcDasecKO mice." (PMID 38302493, 2024). "A single-cell study demonstrated that TREM2+ macrophages within tumours suppressed CD8+ T-cell functions, contributing to tumour immune escape." (PMID 38303024, 2024). "Blocking or targeting TREM2 gene can change the tumor immune environment by enhancing T-cell effector function, enhancing the effect of anti-PD-1 immunotherapy." (PMID 38725629, 2024). "As a surface receptor, TREM2 plays a significant part in macrophage-mediated tumor immune responses, including phenotypic switching and phagocytosis." (PMID 39135069, 2024). "In multiple tumours, TREM2 expression is negatively correlated with the infiltration of immune cells, including dendritic cells, lymphocytes, and NK cells." (PMID 38303024, 2024). "And, TREM2+ macrophages inhibit T cell function and reduce the anti-tumor capacity of CD8+ T cells, which leads to poor response of UC to ICIs treatment." (PMID 38725629, 2024). "All in all, TREM2 can promote tumor growth by promoting T-cell dysfunction and tumor immune escape, and is an important pathology-inducing immune signaling hub." (PMID 38725629, 2024).
tumor (continued). "Although exhibiting less pronounced impacts in these areas than in tumor tissues, TREM2 on CD8+ T cells are still considered to play a broad immunosuppressive role." (PMID 38948071, 2024). "Conversely, combining TREM2 blockers with exogenous NK cell enhancers will further enhance the anti-tumor response and enhance the therapeutic effect of anti-tumor immunity." (PMID 38725629, 2024). "Herein, we found that TREM2-mediated phagocytosis of tumor cells was dependent on the DAP12-Src-Syk signaling pathway, which was inhibited by galectin-3 in LLC CM." (PMID 39135069, 2024). "Functionally, the galectin-3 inhibitor GB1107 alleviated the inhibitory effect of tumor cell-CM on TREM2-mediated phagocytosis." (PMID 39135069, 2024). "Currently, tumor cells and immune cells such as macrophages and dendritic cells with high expression of TREM2 are thought to fulfill momentous functions in avoiding immune surveillance and the resolution of latent inflammatory responses through multiple ways." (PMID 39075517, 2024). "We employed the CellphoneDB software to further investigate the cell types associated with TREM2+ Macrophages and exhausted CD8+ T cells within tumor tissues." (PMID 38948071, 2024). "Our findings revealed that TREM2 promotes macrophage-mediated phagocytosis of tumor cells but is inhibited upon treatment with LLC CM." (PMID 39135069, 2024). "Targeted inhibition of TREM2 can affect the phenotype and function of TAMs and enhance the efficacy of tumor immunotherapy." (PMID 38725629, 2024). "The expression of the chemokine CCL15 displayed a positive correlation with disease progression, and the deconvolution results revealed a highly positive correlation between the proportion of tumour cells and the proportion of TREM2+ macrophages." (PMID 37994257, 2024). "Recently, a report reveals a novel mechanism that ART inhibits the activity of TREM2 in macrophages and suppresses on tumor growth." (PMID 38774917, 2024). "In TME, the expression of TREM2 on TAMs as well as DCs can promote tumor growth by influencing the T cell-mediated immune response and facilitating immune escape from tumors." (PMID 38725629, 2024). "By contrast, highly expressed genes in cluster I10 included multiple known pro-tumor markers in macrophages, such as TREM2, CX3CR1, and SPP1." (PMID 38167466, 2024). "Because of the tissue variability of TREM2 expression, more studies are needed in the future to explore the expression of TREM2 in different cancers as a way to better improve the efficacy of cancer therapy and control tumor progression." (PMID 38725629, 2024). "Overexpression of TREM2 promotes the differentiation of NK cells and enhances their killing activity against tumor cells by activating the PI3K/Akt signaling pathway." (PMID 38725629, 2024). "In a mouse model, targeting TREM2 effectively slowed tumor size and resulted in a better response to anti-PD-1 antibodies." (PMID 39068459, 2024). "Differential expression analysis between macrophages from the tumor and normal tissue identified genes that are enriched specifically within TAMs (TREM2, GPR84 and SPP1) and tissue-resident macrophages (LYVE1), which is consistent with previous observation." (PMID 38349405, 2024). "Our findings strongly support the notion that distinct TAM phenotypes expressing TREM2 can coexist in the tumor microenvironment, exerting different roles, and contributing to the unclear dual function of TREM2 in cancer prognosis." (PMID 38972873, 2024). "Several types of tumor-associated macrophages (TAM), such as FOLR2+ (Folate receptor beta) and TREM2+ (Triggering receptor expressed on myeloid cells 2) TAM have been identified." (PMID 38272907, 2024). "The complex and context-dependent function of TREM2-expressing macrophages in the tumor microenvironment underscores the need for further research to fully understand its contribution to cancer progression and its potential as a therapeutic target." (PMID 38972873, 2024).
tumor (continued). "Genes such as APOE, TREM2, VENTX, and C1QA are associated with tumor growth and progression, promotion of apoptosis, and inflammation." (PMID 38910324, 2024). "To explore the regulatory function of TREM2 on mononuclear macrophages in tumor progression, we established a monocyte co-injection model in CD45.1 mice." (PMID 39135069, 2024). "By using anti-TREM2 monoclonal antibody treatment, tumor growth can be inhibited and a strong anti-tumor immune effect can be produced, which enhances the activation function of CD8+ TIL and anti-PD-1 immunotherapeutic response." (PMID 38725629, 2024). "In recent years, TREM2, a myeloid receptor, has been found to play an important role in altering tumor myeloid infiltrates as well as decreasing the efficacy of immunotherapy." (PMID 38725629, 2024). "TREM2+ cells have been shown to have beneficial properties in hepatic and renal tissue damage, but blockade of these cells restores anti-tumor immunity." (PMID 39867899, 2024). "This study identified that abundant TREM2+ macrophages were recruited at the intra-tumor site through the CCL2-CCR2 chemotactic axis." (PMID 39135069, 2024). "Compared to other CD8+ T cells, CD8+ Tex cells exhibited a pronounced deficiency of inhibitory and stimulatory ligand-receptor pairs, when interacting with TREM2+ Macrophages in tumor tissues." (PMID 38948071, 2024). "Inhibiting the TREM2 gene can trigger the anti-tumor activity of GBM myeloid cells, increase interferon-γ induced immune activation, and promote pro-inflammatory phenotypes, ultimately inhibiting tumor growth and prolonging survival." (PMID 38725629, 2024). "In GC, PRAD, and RCC tissues, TREM2 can promote tumor cell progression by activating the PI3K/Akt signaling pathway." (PMID 38725629, 2024). "It was also found that TREM2-positive TAMs produced a greater amount of galectin-1, which influences PD-L1 overexpression in tumor vessels, and attenuates CD8+ T cell infiltration." (PMID 39408564, 2024). "Noticeably, TREM2 expression levels also vary significantly among different tumor cells, and it can regulate tumor progression by modulating various signaling pathways." (PMID 38725629, 2024). "In different tumor cells, TREM2 expression levels vary significantly and can promote or inhibit tumor progression through different signaling pathways, such as NF-κB, JAK/STAT3 and PI3K/Akt signaling pathways." (PMID 38725629, 2024). "Tumor-educated TREM2+ macrophages are converted into M2-like TAMs by interacting with the novel ligand galectin-3 enriched in the TME." (PMID 39135069, 2024). "anti-Csf1r effectively hinders the accumulation of Trem2+ Macrophages in HCC tumor tissues and synergistically enhances the therapeutic efficacy of anti-PD-1." (PMID 38948071, 2024). "TREM2, a key target for regulating the tumor immune microenvironment, is important in cancer treatment and progression." (PMID 38725629, 2024). "TREM2-expressing macrophages are known to foster a suppressive immune microenvironment, and TREM2 inhibition attenuates tumor growth in a preclinical model when combined with PD-1 inhibitors." (PMID 38424167, 2024). "Genetic deletion of Trem2 or therapeutic blockade by anti-TREM2 antibody administration reduced tumour growth in mainly transplantable cancer models." (PMID 39430099, 2024). "It has been demonstrated that depletion of TREM2+ LAMs in the tumour microenvironment can potentiate the efficacy of anti-PD1 therapy in a mouse breast cancer model." (PMID 38303024, 2024). "High levels of TREM2+ monocytes can reduce tumor load by enhancing tumor phagocytosis and inhibiting inflammatory responses, and exhibit longer survival." (PMID 38725629, 2024). "Monocyte-derived (mo)TAM (for example TREM2+ TAM) infiltrate the tumour core, whereas tissue-resident-derived TAMs (such as FOLR2+ TAM) are predominately located within the perivascular niche of the tumour stroma." (PMID 39430099, 2024).
tumor (continued). "In summary, based on the different expression profiles and physiological functions of TREM2 and the heterogeneity of different cancer types, TREM2 exerts contrasting effects on tumor progression." (PMID 39135069, 2024). "In other solid tumors, such as colon, stomach and pancreas tumor, TREM2+ macrophages accumulate in tumor tissues and promote carcinoma cell growth." (PMID 39113887, 2024). "The steady enrichment of TREM2+ TAM subsets in tumors indicates that TAMs can inhibit anti-tumor immune responses, providing potential targets for immunotherapy." (PMID 37187731, 2023). "To understand the spatial localization of TREM2+ cells in relation to the different tumor epithelial states, we co-stained for TREM2 and LY6D in human BCCs." (PMID 37164949, 2023). "In a mouse tumor model, TAM-expressed TREM2 was associated with increased CD8 Tex and immunotherapy resistance and targeting TREM2 on TAMs synergized with anti-PD1 immunotherapy." (PMID 37187751, 2023). "Multiplex immunofluorescence showed that TREM2+ TAMs were scarce in normal tissues but abundant in tumor tissues." (PMID 37187751, 2023). "The identified TYROBP→TREM2→A2M→APOE→APOC1 cascade is supported by the reports that TREM2 is expressed in tumor macrophages in over 200 human cancer cases and that there are interactions between TREM2/A2M, TREM2/APOE, A2M/APOE, and APOE/APOC1." (PMID 37129360, 2023). "Regarding changes in cell composition, the tumor samples had significantly higher cell proportions of TREM2+ TAMs than the adjacent normal tissue." (PMID 37187751, 2023). "Blocking TREM2 has shown promising anti-tumor effects in tumor patients and mouse models by reprogramming tumorigenic macrophages into anti-tumor macrophages, improving their impaired antigen presentation ability and inhibiting tumor growth." (PMID 37187731, 2023). "Trem2 blocking antibodies enhance tumor immunotherapy action through modulating the cancer microenvironment." (PMID 38646596, 2023). "Studies conducted on mice reveal that TREM2+ macrophages dampen the anti-tumor activities of CD8+ T cells and NK cells, signifying bona-fide immunosuppressive functions for these cells." (PMID 37771596, 2023). "Overall, these data support directed Trem2+ intratumoral maturation of myeloid cells within the tumor." (PMID 37164949, 2023). "This work defines a self-propagating proliferative tumor-immune niche, further supporting ongoing efforts to simultaneously target TREM2+ macrophages to enhance ICB-mediated therapies." (PMID 37164949, 2023). "Five or seven days after transplantation, we found that these injected monocytes expressed substantial levels of both Trem2 as well as the tumor-specific SCAM marker, Vcam1, compared to the monocytes before injection." (PMID 37164949, 2023). "Double staining for CD163 and TREM2 revealed a population of TREM2+ macrophages distributed in the tumor stroma and within tumor nests." (PMID 37370706, 2023). "In murine tumor models, genetic ablation of TREM2 decreased the number of intra-tumoral immunosuppressive TAMs and noticeably improved the efficacy of an anti-PD-1 treatment." (PMID 36845555, 2023). "Lineage prediction tools clearly showed a differentiation transition from monocytes to SCAMs, corresponding with an opening of Trem2-specific peaks suggesting that the transition to a SCAM fate likely occurs within the tumor." (PMID 37164949, 2023). "Triggering receptor expressed on myeloid cells 2 (TREM2), upregulated on TAMs in human and mouse tumours, is a potential target." (PMID 37965573, 2023). "Having confirmed the activities of PD-1 scFv, TREM2 scFv, and BsAb in vitro, the anti-tumor efficacy of the BsAb was further analyzed in a CRC mouse models in vivo." (PMID 37563723, 2023). "In two distinct GBM mouse models, TREM2 knockout resulted in improved overall survival, decelerated tumor progression, and an increase in the number of apoptotic cells within the tumors, hinting at TREM2’s role in TAM-mediated tumor growth inhibition." (PMID 38203185, 2023).